APOBEC3A (apolipoprotein B mRNA editing enzyme catalytic subunit 3A)
Diseases named in the same sentence as APOBEC3A in open-access papers (continued):
Sharing a sentence is not in itself a finding about the gene and the disease.
cancer (continued). "Immunohistochemistry showed that the expression of APOBEC3A was significantly higher in cancer tissues than in normal tissues." (PMID 38021159, 2023). "Dysregulation of many genes, e.g., APOBEC3A, promote evolution and progression of cancers, escape adaptive immune responses, and lead to development of drug resistance in multiple cancers." (PMID 36775056, 2023). "The PI3K-Akt signaling pathway, the mitogen-activated protein kinase (MAPK) signaling pathway, and pathways in cancer were significantly downregulated by APOBEC3A." (PMID 38021159, 2023). "APOBEC3A and APOBEC3B are the prominent mutagenic drivers in several cancer types, giving rise to a distinct mutational signature (SBS2 and SBS13) that can be distinguished from dMMR and identified by cancer genome sequencing and analysis." (PMID 38201511, 2023). "More recently, it has been shown that APOBEC3A is a more potent mutagenic agent than APOBEC3B, and that APOBEC3A signatures are far more frequent in human cancers than APOBEC3B-attributed mutations." (PMID 36980505, 2023). "Random forest algorithm showed that in pan-cancer, APOBEC3B acts as the most important contributor to TCW mutation, and both APOBEC3A and APOBEC3B make the greatest contributions to AMES." (PMID 35673559, 2022). "APOEBC signature, which is derived from APOBEC3A and APOBEC3B cytosine deaminase activities, is one of the most common mutation signatures in different types of cancer, and it has been reported to be associated with tumorigenesis and drug resistance." (PMID 36439454, 2022). "Our results demonstrate that APOBEC3A expression, activity and mutagenesis can be increased by the loss of APOBEC3B in some cancer cell lines." (PMID 35859169, 2022). "Data from other cancers have shown that APOBEC3B is the primary enzyme responsible for APOBEC signature-related mutations, whereas APOBEC3A seems to be inducing DNA damage via double-strand breaks to a higher extend than APOBEC3B17." (PMID 35902635, 2022). "APOBEC3A-induced PD-L1 upregulation requires its deaminase activity and suggests APOBEC3A as an immune evasion mechanism and a potential target for improving cancer therapeutic efficacy of PD-1/PD-L1 targeting therapy." (PMID 36210388, 2022). "APOBEC3A, APOBEC3B, and APOBEC3H are most tightly linked to carcinogenesis due to their frequent expression in cancers, nuclear localization, and ability to deaminate cytidines in genomic DNA." (PMID 36970060, 2022). "Our group demonstrated that certain therapeutics can induce APOBEC3A expression, leading to sustained mutagenesis in drug-tolerant cancer cells." (PMID 36210388, 2022). "Increasing evidence combined with existing knowledge of the role APOBEC plays in mutagenesis in multiple cancer types strongly suggests APOBEC3A as a mediator of tumor response to therapy across multiple tumor types." (PMID 36210388, 2022). "Regarding cancer, at least two APOBEC3 enzymes, APOBEC3B and APOBEC3A, are prominent sources of mutation capable of influencing clinical outcomes." (PMID 36374108, 2022). "A germline 29.5-kb deletion variant removes the 3’ end of the APOBEC3A gene and a large part of APOBEC3B, creating a hybrid gene that has been linked to increased APOBEC3 activity and DNA damage in human cancers." (PMID 34873230, 2021). "In particular, APOBEC3A (A3A) has emerged as a major driver of mutagenesis in cancer cells, and its expression results in DNA damage and susceptibility to treatment with inhibitors of the ATR and CHK1 checkpoint kinases." (PMID 33788831, 2021). "Emerging evidence has suggested that the expression of m6A regulators was critical for carcinogenesis and cancer development, which strengthened the important position of APOBEC3A in OC." (PMID 34745121, 2021). "While many cancer types with APOBEC mutational signatures are solid tumor types, such as breast cancer, the similar role of APOBEC3A has also been shown in a liquid tumor, AML." (PMID 36618446, 2021).
cancer (continued). "APOBEC3A is a cytidine deaminase driving mutagenesis, DNA replication stress and DNA damage in cancer cells." (PMID 32532990, 2020). "While the APOBEC3A-induced vulnerability of cancers offers an opportunity for therapy, APOBEC3A protein and mRNA are difficult to quantify in tumors due to their low abundance." (PMID 32532990, 2020). "We focus on APOBEC3A, APOBEC3B and APOBEC3H haplotype I because they are the leading candidates as sources of somatic mutations in these and other cancers." (PMID 33292100, 2020). "The DNA cytosine deaminases APOBEC3A and APOBEC3B have emerged from cancer genomics studies as drivers of mutation in cancers and tumor heterogeneity." (PMID 32532990, 2020). "We also found that, across cancer types, the germline APOBEC3A/B deletion led to decreased expression levels of uc003awn and uc003awo but caused an increased expression level of uc011aoc." (PMID 31533728, 2019). "Nevertheless, our results showed a strong association between the expression of the isoform and germline APOBEC3A/B deletion in breast and other cancer types, indicating the reliability of these findings." (PMID 31533728, 2019). "Here, we show that ssDNA intermediates formed during the repair of gamma-induced bursts of double-strand breaks (DSBs) in the presence of APOBEC3A in yeast lead to multiple APOBEC-induced clusters similar to cancer." (PMID 31568516, 2019). "Deregulated APOBEC3A expression in cancer is believed to induce double strand breaks in genomic DNA activating DNA damage response pathways." (PMID 31019223, 2019). "One of the most prominent upregulated genes in the NDL-PCB congeners was APOBEC3A, which is involved in oncogenesis of a sizeable proportion of human cancers." (PMID 31200452, 2019). "A strong positive and highly significant correlation between APOBEC3B and APOBEC3A expression was also observed in the pan-cancer analysis (ρ = 0.714, padj < 0.001, n = 1036, Ntests = 10)." (PMID 29642934, 2018). "It was recently shown that APOBEC3A/B expressing cancer cells are sensitive to ATR inhibitors owing to the resulting replication catastrophe." (PMID 30417129, 2018). "Human cancer genomes show signatures that provide clues as to etiological agents, e.g., benzo(a)pyrenes in tobacco smoke, ultraviolet light or endogenous APOBEC3A (A3A) or APOBEC3B (A3B) cytidine deaminases." (PMID 29963239, 2018). "Expression levels of APOBEC3B showed strong and statistically significant positive correlation with APOBEC3A expression in 21 cancer categories (ρ between 0.576 and 1.000; padj < 0.05)." (PMID 29642934, 2018). "Several other cancer types had increased levels of expression of the APOBEC3B gene, but their mean expression levels of APOBEC3A were comparable to the mean APOBEC3A expression across all cancer types." (PMID 29642934, 2018). "Two members of the APOBEC family, APOBEC3A and APOBEC3B, contribute substantially to mutations in cancers by deaminating cytosines in the TpCpW context." (PMID 30514953, 2018). "Here, we discuss current understanding of APOBEC3A and APOBEC3B biology in HPV restriction, evolution, and associated cancer mutagenesis." (PMID 28825669, 2017). "The expression of APOBEC3A or CDA positively correlated the most with C>U RNA editing in cancer tissues, MEPs or macrophages." (PMID 25898173, 2015). "The involvement of AID and APOBEC3A and 3B in cancer suggests that enzymatic deamination of genomic targets is an infrequent but recurrent consequence of the presence of the deaminases in vertebrates." (PMID 25237741, 2014). "APOBEC3 enzymes, including APOBEC3A (A3A) and APOBEC3B (A3B), induce mutations in viral DNA, effectively inhibiting viral replication but also promoting somatic mutations in the host genome, contributing to cancer development." (PMID 40143363, 2025).
cancer (continued). "Moreover, it can be used for the measurement of kinetic parameters, screening of APOBEC3A inhibitors, and quantification of APOBEC3A activity at the single-cell level, with promising applications in cancer diagnosis." (PMID 39589999, 2024). "APOBEC3A is a prominent source of mutagenesis across many cancer types." (PMID 38886582, 2024). "APOBEC3A and APOBEC3B expression is detected in many cancer types and their own classified Catalogue of Somatic Mutations in Cancer (COSMIC) mutational signatures [single base substation signatures (SBS) 2 and 13] are present in over 50% of human cancer types." (PMID 38976757, 2024). "Antiviral DNA cytosine deaminases APOBEC3A and APOBEC3B are major sources of mutations in cancer." (PMID 38499542, 2024). "Nevertheless, APOBEC3A appeared to be the main contributor, as suggested in primary cancers." (PMID 38552621, 2024). "Furthermore, previous works have shown that HPV-associated cancers are associated with a APOBEC3 mutational signature and APOBEC3A/B deletion, and that APOBEC3-mediated mutations are present in HPV genomes." (PMID 36980505, 2023). "Ectopic APOBEC3A expression may hinder cancer evolution at the mutagenesis stage because of its powerful mutagenic role." (PMID 38021159, 2023). "APOBEC3A inhibitors may therefore comprise a unique class of anti-cancer agents that work by blocking mutagenesis, slowing tumor evolvability, and preventing detrimental outcomes such as drug resistance and metastasis." (PMID 37821454, 2023). "The normally antiviral enzyme APOBEC3A is an endogenous mutagen in human cancer." (PMID 37821454, 2023). "APOBEC3A inhibitors may therefore comprise a novel class of anti-cancer agents that work by blocking mutagenesis, preventing tumor evolvability, and lessening detrimental outcomes such as drug resistance and metastasis." (PMID 36824964, 2023). "Considering that the APOBEC family members, including APOBEC3A and APOBEC3B, catalyze mutation and promote cancer growth, we chose the APOBEC activity-related mutational signatures, SBS2 and SBS13, to investigate the differences of the immune microenvironment among clusters." (PMID 35924239, 2022). "Notably, more than 4,000 off-targets have been found upon APOBEC3A overexpression, which is certainly a critical issues given the involvement of APOBECs in processes including cancer development." (PMID 36107771, 2022). "HPV positive cancers also exhibit increased levels of APOBEC3A which is the result of E7-mediated protein stabilization through inhibition of cullin-RING-based E3 ubiquitin ligase which mediates APOBEC3A degradation." (PMID 34578402, 2021). "The cytidine deaminase APOBEC3A is a main source of mutagenesis in many types of cancer." (PMID 34389714, 2021). "In order to further demonstrate the role of APOBEC3A in influencing immune microenvironment of OC, we separated cancer patients into two different APOBEC3A expression cohorts according to the median level and finally identified 187 DEGs by comparing these two groups." (PMID 34745121, 2021). "The high frequency of mutations mediated by APOBEC3A and 3B in HPV positive cancers suggest they may contribute to malignant progression." (PMID 34578402, 2021). "While the mutational spectrum induced by all APOBEC enzymes is not fully understood, the activity of the better-understood APOBEC3A and 3B enzymes in human cancers is distinctly characterised by a strong sequence context, leading to C>T and C>G changes almost solely at TpC sites." (PMID 34387545, 2021). "In a complementary approach from a pan-cancer analysis by Buisson and colleagues, specific DNA secondary structure features were shown to facilitate APOBEC3A-mediated mutagenesis and further utilised to build a statistical model for prediction of APOBEC-related hotspot passengers." (PMID 32988402, 2020).
cancer (continued). "Strikingly, a germline deletion linking APOBEC3A and APOBEC3B loci, which enhances APOBEC3A expression and APOBEC-derived mutagenesis in cancer, has been associated with higher neoepitope loads and immunologic infiltrate and negatively correlated with LNM in BC." (PMID 33352945, 2020). "APOBEC3A and APOBEC3B overexpression has been associated with localised C-to-T and/or C-to-G hypermutations termed “kataegis” in a number of cancers, suggesting that these signatures are important in cancer mutagenesis." (PMID 31547885, 2019). "The SBS2 and SBS13 mutations generated in the cancer cell lines in vitro were largely enriched in the YTCN/YTCA sequence context (where Y is a pyrimidine), consistent with episodic mutagenesis mainly being mediated by APOBEC3A (STAR Methods)." (PMID 30849372, 2019). "The transversions associated with APOBEC1, APOBEC3A, and APOBEC3B were found to be more abundant in comparison with APOBEC3G and AID, suggesting a role of these three deaminases in generating C:G>G:C somatic mutations in human cancer." (PMID 30759888, 2019). "That the APOBEC3A, APOBEC3B, and APOBEC3G footprints are more abundant in comparison with the APOBEC1 and AID motifs suggests an important role for these three deaminases in generating somatic C:G>A:T mutations in human cancers." (PMID 30759888, 2019). "Low expression levels of APOBEC3A in nearly all cancer categories and of APOBEC3B in specific cancer categories may provide high levels of noise in correlation analyses, and therefore, association results for these genes should be interpreted with caution." (PMID 29642934, 2018). "Furthermore, there is a high prevalence of APOBEC3A and APOBEC3B mutation signatures in HPV-associated cancers." (PMID 28825669, 2017). "APOBEC3A could induce hypermutation of genomic DNA and DNA double strand breaks, and catalyze the transition from a healthy to a cancer genome." (PMID 25502777, 2014). "Having observed strong correlations between APOBE3CA expression and GRHL3 expression and predicted activity in single-cell data from HNSCC and ESCC, we next sought to determine whether GRHL3 may be involved in regulating APOBEC3A expression cancer arising in other tissues." (PMID 39548236, 2025). "Given the extensive overlap between the molecular processes that are active during wound healing and cancer, this latter function may be of particular relevance to driving APOBEC3A expression in tumour cells, including in those undergoing DNA replication and warrants further investigation." (PMID 39548236, 2025). "APOBEC3A is also a source of cancer mutation in viral and nonviral tumor types." (PMID 37474103, 2023). "Thus, APOBEC3B may regulate APOBEC3A mutagenesis across a broader range of cancers, possibly through regulating the expression of APOBEC3A." (PMID 35859169, 2022). "The mutagenic activity of APOBEC3A (A3A) and APOBEC3B (A3B) has recently been demonstrated to introduce somatic mutations in genomic DNA, and those two enzymes are now recognized as endogenous causal agents responsible for the accumulation of CG to TA transitions in cancer genomes." (PMID 34403699, 2021). "An enrichment of mutational motif specific to APOBEC3A compared to other APOBEC family members has been defined as an “A3A‐like” signature; notably, this signature can be distinguished from other APOBEC enzyme signatures in multiple cancer types with high levels of APOBEC‐driven mutations." (PMID 36618446, 2021). "Indeed, the extended sequence context in which SBS2 and SBS13 mutations occur in human cancers is predominantly that at which APOBEC3A, rather than APOBEC3B, induces mutations in yeast (TCN preceded by a pyrimidine base rather than a purine)." (PMID 30849372, 2019).
cancer (continued). "As two human ssDNA cytidine deaminases APOBEC3A (A3A), APOBEC3B (A3B) and related enzymes across the spectrum of placental mammals have been shown to introduce somatic mutations into nuclear DNA of cancer genomes, we explored the mutagenic threat of A1 cytidine deaminases to chromosomal DNA." (PMID 31726973, 2019). "To address this question, we investigated the presence of APOBEC3B-like mutational patterns and mRNA expression of the APOBEC3A, APOBEC3B, UNG, REV1, and FHIT genes in cancer cell lines, in order to identify those cancer cell lines that may have experienced kataegis events." (PMID 29642934, 2018). "Indeed, while expression levels point towards APOBEC3B as the guilty party, the increase in cancer risk among germline APOBEC3B deletion carriers and the increased burden of APOBEC-pattern mutations attributed to APOBEC3A seen in these patients highlights key unresolved issues." (PMID 27716362, 2016). "Before kataegis was described, genome sequencing studies had revealed that many cancers have somatic mutations dominated by C-to-T transitions and that overexpression of APOBEC1 was associated with cancer development when overexpression of APOBEC3A induced genomic damage and mutations." (PMID 24966870, 2014). "In recent years, members of the APOBEC3 family, particularly APOBEC3A and APOBEC3B, have been studied as mutagenic drivers in cancer, although only a few studies have examined the functional role of APOBEC-induced mutagenesis." (PMID 41390483, 2025). "Maintaining genome stability in the presence of active APOBEC3A involves SMC5/6-dependent stabilization of forks with single-strand gaps, suggesting a potential vulnerability of cancer cells." (PMID 38886582, 2024). "The APOBEC3A and APOBEC3B anti-viral genes show increased expression in both precancer and cancer compared to controls (p < 0.0001, p < 0.0001)." (PMID 39672307, 2024). "APOBEC3A and APOBEC3B are overexpressed in many cancers, and their expression correlates with a higher APOBEC3-induced mutation burden." (PMID 36978147, 2023). "Of note, APOBEC1 and APOBEC3A expression were only detected in a handful of cancers, such as APOBEC1 in PAAD, in contrast to APOBEC3G, which was detected in most cancer types." (PMID 36969056, 2023). "Examination of gene expression measures in the pan-cancer dataset showed a bimodal distribution of APOBEC3B expression, whereas APOBEC3A, REV1, UNG, and FHIT had unimodal distributions of their expression measures." (PMID 29642934, 2018). "APOBEC3A and APOBEC3B enzymes able to target genomic DNA are involved in oncogenesis of a sizeable proportion of human cancers." (PMID 29963239, 2018). "We observed a bimodal distribution of APOBEC3B expression and unimodal distributions of APOBEC3A, REV1, UNG, and FHIT in the pan-cancer dataset." (PMID 29642934, 2018). "The APOBEC family of enzymes are cytidine deaminases with APOBEC3A and APOBEC3B thought to contribute to DNA damage signatures detected in cancer genomes." (PMID 27650891, 2016). "APOBEC3A (A3A) can access and edit nuclear DNA (nuDNA), suggesting a role for APOBEC3 enzymes in DNA catabolism and perhaps cancer." (PMID 23977391, 2013). "Moreover, it is unlikely that chronologically discrepant episodic APOBEC3A mutagenesis and UNG/BER induction show similar findings across all cancer types and multiple BER enzymes." (PMID 38617360, 2024). "Although, if APOBEC3A’s editing activity is not required for its role in ribosome biogenesis, as our results suggest, these inhibitors would be unlikely to alter this aspect of APOBEC3A’s cancer promoting ability." (PMID 38976757, 2024). "Moreover, both APOBEC3A and APOBEC3B display cytidine-deaminase-independent roles in carcinogenesis that add complexity when it comes to comprehending their roles in cancer." (PMID 36980505, 2023).